GPRC5A (G protein-coupled receptor class C group 5 member A)
Diseases named in the same sentence as GPRC5A in open-access papers (continued):
Sharing a sentence is not in itself a finding about the gene and the disease.
cancer (continued). "In recent years, one member, GPRC5A, has been receiving increasing attention as it was shown to play important roles in human cancers." (PMID 25621293, 2014). "GPRC5A shows potential as a prognostic biomarker and therapeutic target in specific cancers." (PMID 39006081, 2024). "Related research on hypoxic cancer cells showed that YAP can be activated by GPRC5A, a novel hypoxia-induced protein that protects cancer cells from apoptosis during oxygen deprivation, leading to the downregulation of proapoptotic target genes and the increased survival of hypoxic cancer cells." (PMID 35606801, 2022). "In this meta-analysis, fourteen studies demonstrated the correction between GPRC5A expression and OS in human cancer pooled HRs with 95%CIs evaluated for OS was (1.69 95%CI 1.20–2.38 p = 0.05), using a random-effects model for high heterogeneity (I2 = 75.6% P< 0.001)." (PMID 33788883, 2021). "The effect of GPRC5A in various cancers has been reported to be different." (PMID 33788883, 2021). "However, with the development of screening technologies, the extreme abnormal expression of GPRC5A has been noticed in different cancers." (PMID 33753999, 2021). "In mouse cancer cell lines and E-coli-related cancer models, it was found that after oxidative stress-related pathways were abnormally regulated, GPRC5A deletion would reduce cell proliferation, increase cell apoptosis, and inhibit the occurrence of tumors in vivo." (PMID 33505587, 2021). "In summary, our results suggest that GPRC5A can be a promising candidate for predicting medical outcomes and used for accurate diagnosis, prognosis prediction for patients with cancer; however, the predictive value of GPRC5A varies significantly according to cancer type." (PMID 33788883, 2021). "Further studies will be needed to reveal novel insights into application of GPRC5A in cancer." (PMID 33788883, 2021). "The IHC experiment conducted on PAAD tissue microarray verified that the positive ratio of both GPRC5A and IMUP were much higher in cancer (74.6 and 46.8% respectively) than matched normal pancreatic samples (both less than 5%), supporting the aberrant gain of expression of GPRC5A and IMUP in PAAD." (PMID 34819098, 2021). "Recently, GPRC5A has been proven to be an essential role in human cancers." (PMID 33788883, 2021). "However, GPRC5A was also found to serve as an oncogene in these cancers, and the high expression of GPRC5A was related to tumorigenesis." (PMID 33788883, 2021). "Recently, GPRC5A has received attention for its intriguing dual behavior in cancer." (PMID 33788883, 2021). "Furthermore, our knockdown results reveal specific contributions of RSK1 and RSK2 in the oncogenic switch, including active RSK1 function in the platinum‐induced GPRC5A regulation coupled to apoptosis evasion of the platinum‐resistant cancer cells." (PMID 32115889, 2020). "This review will focus on recent advances in GPRC5A research and on its role in human cancer." (PMID 30417009, 2018). "Previous work suggested a role for GPRC5A in various cancers." (PMID 29872392, 2018). "Because GPRC5A expression is linked to inhibition of STAT3 and induction of differentiation, restoration of GPRC5A expression may provide a novel strategy for cancer prevention of HNSCC." (PMID 28270740, 2017). "For further characterization the expression of GPRC5A in cancer cell lines, we examined the protein levels of GPRC5A in one normal cell line, HOK, and six different head and neck squamous cell lines, HN12, HN13, CAL27, SCC-25, SCC-15 and HN30, by immunoblot analysis." (PMID 28270740, 2017). "Lastly, we evaluate the impact of GPRC5A knockdown on the cancer cells' sensitivity to gemcitabine." (PMID 27415424, 2016). "Previous GPRC5A studies indicated that it plays important roles and that its dysregulation could result in many different types of cancer in humans as well as other diseases." (PMID 25621293, 2014).
cancer (continued). "GPRC5A is dysregulated in several human cancers and may be a candidate target for cancer treatment." (PMID 33788883, 2021). "However, the influences of GPRC5a on different cancers vary." (PMID 29949874, 2018). "A recent study proves that the Sca-1+Abcg1+ bronchioalveolar epithelial cells are the cancer stem cell-like subset of AT2 cells and are the origin of LADC in GPRC5A-knockout mice." (PMID 32771979, 2020). "Recently, G protein-coupled receptor family C group 5 member A (GPRC5A), a member of class C orphan GPCRs, has been found to be dysregulated in several human cancers." (PMID 30417009, 2018). "Mechanistic studies revealed that GPRC5A promotes the activity of the oncoprotein YAP, a signal transducer from the Hippo signalling pathway with established roles in cancer development." (PMID 30143543, 2018). "In most reported cancers, GPRC5A promotes cancer progression regardless of its up- or downregulation in cells." (PMID 36735162, 2023). "In cancer cells, GPRC5A acts as a negative regulator of PI3K/AKT and cAMP/PKA pathways, and it remains to be seen whether GPRC5A regulates these pathways in adipose tissue." (PMID 36766718, 2023). "It has been suggested that highly expressed GPCRs in cancer cells (e.g., GPRC5A in PDAC and colon cancer cells and GPR68 in PDAC CAF) may contribute to malignant phenotypes and may be novel therapeutic targets for cancer as biomarkers." (PMID 35885996, 2022). "GPRC5A expression in PDAC appears to be mostly limited to the cancer cells and not present in the surrounding microenvironment." (PMID 34522225, 2021). "In conclusion, based on multiple GEO database and bioinformatic analysis tools, we identified 22491 genes that were differently expressed in PAAD comparing to normal pancreatic tissues, and highlighted 2 genes of them: GPRC5A and IMUP as independent prognostic indicators in cancer development." (PMID 34819098, 2021). "The exact role of GPRC5A, both in cancer and normal conditions, has not been fully elucidated, though it is thought to be related to cell cycle progression and involvement of this protein in several signaling pathways." (PMID 34522225, 2021). "Firstly, an online Ualcan service was used, and the result showed that not only the GPRC5A and IMUP genes expression were markedly higher in cancer comparing to normal samples, but also the expression of both genes keep increasing as the cancer stage and grade advancing." (PMID 34819098, 2021). "In line with the contrasting expression, recent analysis of GPRC5A function revealed a controversial role in different cancer entities: Expression of GPRC5A in non-tumorigenic pancreatic epithelial cells promoted colony formation." (PMID 32719397, 2020). "Another transcription factor MYC also binds to GPRC5A promoter region in some cancer cells like HeLa and HepG2 cells, whereas not in embryonic stem (ES) cells." (PMID 25621293, 2014). "Finally, although our results showed that the predictive value of GPRC5A varies significantly according to cancer type, we did not further study the mechanisms of this." (PMID 33788883, 2021). "However, the result revealed that none significant correlation was found between GPRC5A gene expression and CD4 + T cell, CD8 + T cell, B cell, NK cell, monocyte, macrophage cell, dendritic cell or cancer associated fibroblast infiltration in PADD." (PMID 34819098, 2021). "The patients with GPRC5A and IMUP genes altered (all types of alteration besides amplification) showed worse overall, disease free and progression free survival than patients without gene alterations, indicating the genes’ potential value in cancer development (data not shown)." (PMID 34819098, 2021).
adenocarcinoma (7 papers, 2010 to 2024). A common cancer characterized by the presence of malignant glandular cells. "GPRC5A is a potential oncogene in adenocarcinoma cells of the pancreatic duct, and knocking out GPRC5A can reduce the proliferation and migration ability of PC cell lines, as well as inhibit their chemoresistance to gemcitabine, oxaliplatin, and fluorouracil." (PMID 38634049, 2024). "In accordance, Mcm2, Fen1, Ube2c and cyclin D1 proteins were also relatively higher in the MDA-F471 mouse adenocarcinoma cells compared to the normal Gprc5a−/− cells as revealed by the western blotting analysis." (PMID 20686609, 2010). "Because gene expression at the mRNA level does not always correspond to protein levels, we then examined the expression of the protein products of Ube2c, Fen1 and Mcm2 in Gprc5a−/− lung normal and adenocarcinoma tissue and cells." (PMID 20686609, 2010). "The incidence of adenocarcinomas in the NNK exposed Gprc5a knockout mice (80%) was much higher than the 17% incidence of spontaneous adenocarcinomas in mice followed for up to 24 months and also higher than that reported previously by others for NNK-treated A/J mice." (PMID 20686609, 2010). "We sought to test the relevance of the differential gene expression patterns between the Gprc5a-knockout MDA-F471 adenocarcinoma and normal lung epithelial cells to the gene expression patterns in publicly available microarray datasets of both mouse and human NSCLC and normal lung tissue." (PMID 20686609, 2010). "A pertinent question is whether the differential gene expression patterns between the Gprc5a−/− adenocarcinoma MDA-F471 cells and the normal lung Gprc5a−/−cells are relevant to human lung carcinogenesis." (PMID 20686609, 2010). "Using comparative functional genomics and functional pathways analysis followed by validation at the protein level by immunohistochemistry and western blotting analyses, we highlighted the marked up-regulation of Ube2c, Mcm2 and Fen1 in Gprc5a-knockout mouse adenocarcinoma relative to normal lung." (PMID 20686609, 2010). "Moreover, the protein expression of several key genes of the NNK-ADC signature was validated at the protein level by immunohistochemistry in histological tissue specimens of normal lung and adenocarcinomas obtained from five Gprc5a knockout mice." (PMID 20686609, 2010). "Furthermore, following principal component analysis in three-dimensional space, the mouse MDA-F471 adenocarcinoma cells resided very closely to the human lung 1170-I tumorigenic cells which together were distant from the mouse Gprc5a−/− normal lung epithelial cells and the human NHBE cells." (PMID 20686609, 2010). "In this study, we show that exposure of Gprc5a-knockout mice to NNK tobacco-specific carcinogen increased the incidence and multiplicity of lung tumors, especially adenocarcinoma, compared to control mice." (PMID 20686609, 2010).
inflammation (3 papers, 2015 to 2023). Aberrant reaction of the microcirculation characterized by movement of fluid and leukocytes from the blood into extravascular tissues. "Lung tumor suppressor gene Gprc5a-knockout (ko) mice are susceptible to lung inflammation, tumorigenesis and metastasis, which resembles the pathological features in human patients." (PMID 32060421, 2020). "Taken together, silica exposure induced production of chemokines in MTEC; which likely contributes to increased recruitment of macrophage and pulmonary inflammation; whereas Gprc5a deficiency further increased the intensity of the response." (PMID 26447616, 2015). "Gprc5a-KO mice are susceptible to pulmonary inflammation and LPS-induced acute lung injury." (PMID 36413416, 2023). "Intra-tracheal administration of fine silica particles in Gprc5a−/− mice resulted in more severe lung injury and pulmonary inflammation than in wild-type mice." (PMID 26447616, 2015).
infection (1 paper, 2024). The state of being infected such as from the introduction of a foreign agent such as serum, vaccine, antigenic substance or organism. "The activation of the S100 signaling pathway, along with the upregulation of candidate receptors, ACKR3 and GPRC5A, are closely associated with acute inflammation caused by GPS infection." (PMID 39202454, 2024).
GPRC5A also shares sentences with these, for which no sentence is quoted: breast tumor (3 papers); nevus (3); pancreatic ductal adenocarcinoma (3); bladder tumors (2); coronary artery disease (2); invasive breast carcinoma (2); leukemia (2); oral cancer (2); serous ovarian carcinoma (2); atherosclerosis (1); benign tumors (1); bladder urothelial carcinoma (1); Carcinogen (1); chronic pancreatitis (1); Colon (1); colon adenocarcinoma (1); cystic neoplasm (1); ductal carcinoma (1); ductal carcinoma in situ (1); endometrial cancer (1); epilepsy (1); esophageal cancer (1); experimental autoimmune encephalomyelitis (1); haematological disorders (1); head and neck cancer (1); inflammatory bowel disease (1); intestinal tumours (1); invasive ductal breast carcinoma (1); ischemia (1); large cell lung cancers (1).
A further 7 diseases each share a sentence with GPRC5A in 1 paper.